TGFA (transforming growth factor alpha)
Diseases named in the same sentence as TGFA in open-access papers (continued):
Sharing a sentence is not in itself a finding about the gene and the disease.
cancer (continued). "Several proteins positively associated with MVPA are inversely associated with disease risk (e.g., integrins, CLEC4A for cancer; LPL, LEP for T2D), while proteins negatively associated with MVPA are positively associated with disease risk (e.g., CD38, TGFA for CVD)." (PMID 41826625, 2026). "Transforming growth factor-alpha has long been recognized as a factor that may contribute to cancer development, particularly due to its role in EGFR activation." (PMID 40410803, 2025). "Besides genetic factors, a hypoxic environment has been shown to induce overexpression of EGFR in cancer and to upregulate both TGFA and VEGF-A in cancer and ECs." (PMID 37199488, 2023). "Depletion of TGFα prohibits rCAF mediated chemoresistance in cancer cells." (PMID 37821657, 2023). "TGFα-EGFR signaling is associated with carcinogenesis and cancer progression." (PMID 35290621, 2022). "TGFα promotes the progression of cancer by increasing proliferation and differentiation." (PMID 34298609, 2021). "Therefore, we compared gene expression for cancer-associated fibroblast (CAF) markers including MMP2, MMP9, MMP21, TGFA, CXCL12, ITGA3, FAPα, and IL32 in fibroblasts derived from normal skin and MF tumors." (PMID 33941102, 2021). "Our study discovered the pro-carcinogenic effect of LINC00857 in PAAD cancer cells, that is, LINC00857 was implicated in the malignancy of PAAD via acting as a ceRNA competitively targeting to miR-340-5p and thereby upregulating TGFA expression." (PMID 33661995, 2021). "TGFA is upregulated in some human cancer cells, which is related to their metastasis and invasion." (PMID 32020849, 2021). "Although the TGFA gene is demonstrated to be involved in cancer cell proliferation and metastasis, its role in cell sensitivity to cisplatin chemotherapy remains unclear." (PMID 32020849, 2021). "Small changes in the activities of WNT and TGFα in cancer cells might therefore have important metastatic outcomes." (PMID 31253868, 2019). "Therefore, it is possible that the TGFα-EGFR signaling axis promotes cancer cell proliferation, invasion, and metastasis, all of which drive the aggressiveness of TNBC and lead to poor response to EGFR inhibitors." (PMID 30034618, 2018). "Initially, development of cancer in mouse pancreas was demonstrated by targeting Myc and TGFα to mouse pancreatic acinar cells (EL-Myc and EL-TGFα), which demonstrated acinar-to-ductal metaplasia leading to exocrine carcinoma with focally distinct ductal-like lesions." (PMID 25538623, 2014). "To characterize such outcomes in a defined setting, we undertook a controlled hepatocarcinogenesis study involving varying levels of dietary selenium and altered selenoprotein status using mice carrying a mutant (A37G) selenocysteine tRNA transgene (TrsptG37) and/or a cancer driver TGFα transgene." (PMID 23460847, 2013). "TGFα has been reported to be able to activate the MAPK signaling pathway in cancer cells." (PMID 22864984, 2012). "In addition, String pathway interaction analysis identified six proteins (TGFBR2, TGFA, FGF21, SMAD4, TGFBR1, and FZD3) that were at the intersection of the cancer-associated pathways and, importantly, which were restored to their younger crosstalks by the rounds of TPE." (PMID 35999337, 2022).
cancer (continued). "Whereas Coffey and co-workers showed that the EGFR ligand amphiregulin is continuously released in exosomes in a signaling-competent state, leading to increased cancer cell invasion, they showed, like us, that TGFα associated with the same vesicles fraction showed no significant activity." (PMID 27264103, 2016). "Since TGFA, IRF6, and p63 are known to be involved in cancer, and in the view of our recent findings that cleft lip and palate families report more cancer, these gene-gene interactions might not only explain susceptibility to oral clefts, but also cancer." (PMID 23029012, 2012). "Binding of ligands, such as epidermal growth factor and transforming growth factor alpha (TGFα), to their extracellular ligand-binding domain initiates intracellular signalling cascades, leading to progression, proliferation, migration, and survival of cancer cells." (PMID 18087285, 2008). "TGFα, a well-established driver of EMT and cancer stem cell properties, plays a crucial role in cancer metastasis and therapeutic resistance." (PMID 40051704, 2025). "Cell‐cell signaling pattern between basal cancer cells (Ca), FPCS, and TPCS revealed that while Ca‐Ca and Ca‐FPC signaling mainly comprised PGF, TGFA, and VEGFA signaling, TPCS uniquely received BMP signals (BMP2/4 and GDF5) from Ca." (PMID 38582099, 2024). "Through cell cycle dysregulation and increased cancer cell survival, the interaction of EGFR with TGFα and EGF promotes tumorigenesis." (PMID 39590368, 2024). "Of note, circ_63706 knockdown downregulated genes contributing to important cancer pathways including RBBP4, TGFA, E2F1, and HRAS." (PMID 36899402, 2023). "Cells from clusters 0/10 have increased expression of Tgfα while those from clusters 5/24 have increased expression of Hbegf —two EGFR ligands that exert differential signaling in cancer models." (PMID 35624211, 2022). "Numerous cancer targets including VEGF, FGF, PGF, EGF, PDGF, topoisomerase I and II, histone deacetylase, tyrosine kinase, and transforming growth factor-alpha (TGF-α) have been elucidated with multiple studies focused mainly on targeting the initiator VEGF." (PMID 34885716, 2021). "S100A2, TGFA, MET, PCNA, SCD, GDF15, and PAI1 act as oncogenes by promoting cancer metastasis or proliferation 24-30." (PMID 34131400, 2021). "PE38 is a recombinant immunotoxin prepared as a conjugate between TGFα and a laboratory-engineered Pseudomonas exotoxin A. The PE38 immunotoxin is under investigation for EGFR-positive cancers, for example brain tumors." (PMID 33738260, 2021). "CAF produce numerous factors acting on cancer cells to promote glycolytic metabolism, proliferation, invasion, angiogenesis and metastatic colonisation, including CCL5, CXCL10, IL‐6, TGFα, SDF and versican." (PMID 34841720, 2021). "Overexpression of TGFα and EGFR is also detected in a variety of human cancers, including epithelial and lung cancers, and gliomas." (PMID 32432044, 2020). "On this note, ADAM17 is associated with shedding of several EGFR family ligands (e.g., EGF, TGFα, and amphiregulin) in NSCLC and other cancers." (PMID 30833304, 2019). "TGFα and EGF stimulate EGFR to induce cell growth signaling in normal condition and are involved in invasive and metastatic condition of cancers." (PMID 30774817, 2018). "A recombinant immunotoxin comprising TGFα and a modified Pseudomonas exotoxin A (PE38) derived from Pseudomonas aeruginosa was developed for treatment of EGFR-expressing malignant tumors, e.g. brain tumors." (PMID 28473665, 2017). "Transforming growth factor alpha (TGFα) is a natural ligand for the EGFR, which plays a central role in cancer development." (PMID 28473665, 2017). "TNF can induce the expression of transforming growth factor alpha (TGF α) and epidermal growth factor receptor (EGFR) in cancer cells." (PMID 27821804, 2016). "Studies investigating the TGFα-EGFR signaling pathways that promote the growth and spread of cancer cells." (PMID 23986907, 2013).
cancer (continued). "We compiled a reliable list of L/R pairs associated with PTC and validated the biological role of one of the emerged L/R pair, the TGFA/EGFR, in this cancer, in vitro." (PMID 20877637, 2010). "Data from these human and animal studies are in line with a generally accepted notion that TGFα is the preferred trophic factor over other EGFR ligands for normal ductal cells and cancer cells in the pancreas." (PMID 16822304, 2006). "Transforming Growth Factor Alpha (TGFA) and Transforming Growth Factor beta (TGFB) are secreted by a wide range of altered cells and malignancies, and then, it is assumed that is an autocrine growth factor in the development and maintenance of cancer." (PMID 36430763, 2022). "In addition, TNF-α upregulates transforming growth factor-alpha (TGF-α), an oncogene that can increase cell proliferation and promote cancer." (PMID 34940031, 2021). "We detected significant molecular signals of transcriptional interference with gene expression induced in human cancer cells in response to multiple growth factors such as epidermal growth factor (EGF), insulin-like growth factor-1 (IGF-1), transforming growth factor alpha (TGFA), and many others." (PMID 35155195, 2021). "TGFα is expressed primarily in ectodermic and epithelial cells during normal development and is frequently up-regulated in carcinoma cells, and expression of TGFα can confer a transformed phenotype and tumorigenesis to normal cells." (PMID 34957124, 2021). "Binding of EGFR with its ligands TGFα or EGF results in autophosphorylation of RTK followed by activation of downstream pathways, including the RAS pathway, that regulate cell proliferation and differentiation in various types of cancer." (PMID 32432044, 2020). "EGFR is overepressed in many cancer types and activated by a variate of ligands, including besides EGF also the transforming growth factor-alpha (TGFA), heparin-binding EGF-like growth factor (HBEGF), betacellulin (BTC), amphiregulin (AREG) and epiregulin (EREG) and epigen (EPGN)." (PMID 32119655, 2020). "Fifteen members of cancer pathways, including FOS, TGFα, FZD8, MMP1, laminin subunit gamma 2, PTGS2, laminin subunit beta 3, ITGA2, laminin subunit alpha 3, VEGFC, WNT2B, heat shock protein 90 beta family member 1, WNT5B, FGF5 and WNT3A, were up-regulated in the MC group." (PMID 30482199, 2018). "Several substrates of ADAM15, including EGFR ligands such as HB-EGF, TGFα, amphiregulin, betacellulin, and other factors including Notch, and cytokines have been identified in cancer cells." (PMID 26930657, 2016). "In addition, the overexpression of TGFα and EGFR by many carcinomas correlates with the development of cancer metastasis, resistance to chemotherapy and poor prognosis." (PMID 23986907, 2013). "This could help block the activity of EGFR ligands implicated in cancer and inflammation (e.g., AREG, EREG,) without affecting the function of TGFα in protection of the skin and intestinal barrier." (PMID 36361585, 2022). "ADAM17 proteolytically cleaves and activates several EGFR ligands such as epiregulin, transforming growth factor alpha (TGF-alpha), amphiregulin (AREG) and heparin-binding EGF-like growth factor (HB-EGF) and may thus contribute to cancer progression through EGFR activation." (PMID 36140519, 2022). "Among ADAM17 substrates, IL‐6R, TNFα, Notch1, and EGFR family ligands (e.g., TGFα, amphiregulin, epiregulin, and neuregulin‐1) promote the proliferation, survival, migration, and/or invasion of tumor cells (Zunke & Rose‐John, 2017), thus suggesting a prominent role for ADAM17 in cancer." (PMID 30833304, 2019). "Taken together, the TGFα-EGFR-Akt signaling axis can play a role in enhancing proinflammatory chemokine expression in TNBC, subsequently contributing to the inflammatory burden that ultimately lead to cancer progression and a higher mortality rate among TNBC patients." (PMID 30034618, 2018).
cancer (continued). "The advantage of using TGFα as the sole cancer driver gene compared to the bi-transgenic cancer driver model is the additional time allotted by the single transgenic model to develop tumors that in turn permitted the control (non-bearing TGFα) mice to also develop tumors." (PMID 23460847, 2013).
infection (29 papers, 2012 to 2025). The state of being infected such as from the introduction of a foreign agent such as serum, vaccine, antigenic substance or organism. "We observe both steady-state and infection-associated induction of pro-inflammatory and pro-fibrotic signaling in the former, including increased expression of TGFA, IL6, IL8, and IL20." (PMID 37874141, 2023). "Our quantitative PCR data showed that three ligands, HB-EGF, AREG and EREG, displayed significant up-regulation at 60 min after infection with strain RS218, while the transcriptional levels of EGF, BTC and TGFα remained unchanged during the infection." (PMID 27711202, 2016). "pylori) infection and overexpression of transforming growth factor-alpha (TGF-a)." (PMID 37868436, 2023). "Notably, IL-33, TGFα, and IL-18 were depleted in end of infection samples compared with the negative controls, indicating a difference in cytokine profile between resolving infection and baseline innate immune status." (PMID 36586415, 2023). "The results showed that the triple deletion mutant was able to induce significant up-regulation of AREG and EREG after 60 min, while there was no up-regulation of HB-EGF, as well as EGF, BTC, and TGFα, after infection with the triple deletion mutant." (PMID 27711202, 2016). "Infection with ZIKV did not produce substantial alterations when compared to baseline levels prior, with the exception of TGFα, IL-1RA, IL-10, and MCP-1." (PMID 30469417, 2018).
inflammation (4 papers, 2020 to 2025). Aberrant reaction of the microcirculation characterized by movement of fluid and leukocytes from the blood into extravascular tissues. "In summary, this study demonstrates the spatio-temporal regulation of TGFα in autoimmune CNS inflammation." (PMID 40537468, 2025). "We identify microglia as the primary source of TGFα in the CNS during autoimmune inflammation, alongside limited and stage-specific expression of TGFα in astrocytes, oligodendrocytes, and neurons." (PMID 40537468, 2025).
neurodegenerative disease (2 papers, 2022 to 2024). A disorder of the central nervous system characterized by gradual and progressive loss of neural tissue and neurologic function. "Transforming growth factor alpha (TGF-α) is crucial in maintaining glutamate transporter function in astrocytes, which provides neuroprotection associated with most neurodegenerative diseases." (PMID 39634607, 2024).
hematologic malignancy (1 paper, 2018). "While TGFα has long been investigated and linked to prognostic survival in many solid tumor types, this is the first evidence that TGFα is an important cytokine in a hematologic malignancy." (PMID 29614027, 2018).
TGFA also shares sentences with these, for which no sentence is quoted: liver fibrosis (10 papers); lung adenocarcinoma (6); viral infection (6); asthma (5); atherosclerosis (5); cholangiocarcinoma (5); head and neck squamous cell carcinoma (5); adenocarcinoma (4); Cirrhosis (4); renal disease (4); breast (3); breast invasive carcinoma (3); clear cell renal carcinoma (3); colitis (3); diabetic nephropathy (3); esophageal cancer (3); gastrointestinal tumour (3); influenza (3); ovarian tumors (3); pneumonia (3); rheumatoid arthritis (3); sarcoma (3); autoimmune disorders (2); Barrett esophagus (2); benign tumor (2); Cachexia (2); Cerebral ischemia (2); cystic fibrosis (2); cystic kidneys (2); diabetic retinopathy (2).
A further 142 diseases each share a sentence with TGFA in 2 papers or fewer.